ARID2 (AT-rich interaction domain 2)
Diseases named in the same sentence as ARID2 in open-access papers (continued):
Sharing a sentence is not in itself a finding about the gene and the disease.
esophageal squamous cell carcinoma (1 paper, 2016). Esophageal squamous cell carcinoma (ESCC) is a type of esophageal carcinoma (EC) that can affect any part of the esophagus, but is usually located in the upper or middle third. "As for esophageal squamous cell carcinomas (ESCCs), somatic mutations have been detected for ARID1A, ARID2, and PBRM1 by exome-sequencing." (PMID 26812616, 2016).
gastric adenoma (1 paper, 2016). A neoplastic polyp that arises from the stomach. "All MSS gastric adenomas also harbored ARID2 truncating mutations, often as multiple, region-specific ones indicative of convergent evolution." (PMID 27175599, 2016).
gastric MALT lymphoma (1 paper, 2024). "However, in our study, the high mutation rate of the ARID2 gene in Hp-negative gastric MALT lymphoma had to draw our attention to the possibility that mutations in this gene may have a crucial role in Hp-negative gastric MALT lymphoma pathogenesis." (PMID 39054516, 2024).
intestinal tumour (1 paper, 2021). "It was shown, that 13% of MSI CRC carried ARID2 variants and studies of intestinal tumour organoids and sporadic colorectal adenomas indicate that ARID2 may function as a TSG." (PMID 34843512, 2021).
learning disabilities (1 paper, 2025). "Overall, the clinical assessment of the newly identified individuals allowed us to define the phenotypic spectrum of ARID2-RD, suggesting that ID is often mild, and when absent, individuals without an ID seem to have learning disabilities or a heterogenous cognitive profile." (PMID 40044822, 2025).
mantle cell lymphoma (1 paper, 2023). Mantle cell lymphoma is a rare form of malignant non-Hodgkin lymphoma affecting B lymphocytes in the lymph nodes in a region called the ``mantle zone''. "In mantle cell lymphoma (MCL), recurrent mutations have been observed in SMARCA4 (mutation frequency ~ 6-10%), ARID2, ARID1A, and ARID1B (mutation frequency ~ 3-6% each)." (PMID 36810086, 2023).
metastatic tumor (1 paper, 2023).
Noonan syndrome (1 paper, 2025). Noonan Syndrome (NS) is characterized by short stature, typical facial dysmorphism and congenital heart defects. "Several articles mentioned a resemblance between the dysmorphic facial features linked to ARID2 and those in RASopathies, such as Noonan syndrome, as in I-7 of this series." (PMID 40044822, 2025).
Obesity (1 paper, 2025). Accumulation of substantial excess body fat. "One of the DMRs overlapped with MC4R associated with autosomal dominant and recessive obesity, a phenotype not described in young individual with ARID2-RD." (PMID 40044822, 2025).
osteoporosis (1 paper, 2019). A condition of reduced bone mass, with decreased cortical thickness and a decrease in the number and size of the trabeculae of cancellous bone (but normal chemical composition), resulting in increased fracture incidence. "The genes identified in our study—LTBP1, PZP, ARID2, and HEBP1 in osteoporosis BRON patients—clearly support the previous evidence that angiogenesis, osteoclast activity, bone remodeling, and immune responses are critical underlying mechanisms." (PMID 31747953, 2019). "Excluding genes without known specific functions (CDC27 and TNRC18), ARID2, HEBP1, LTBP1, and PLVAP were the only significant differences in the cancer group revealed by the gene-score methodology, while DFFA, FAM193A, and VEGFA were the only significant differences in the osteoporosis group." (PMID 31747953, 2019).
papillary adenocarcinoma (1 paper, 2024). A morphologic variant of adenocarcinoma.
prostate carcinoma (1 paper, 2022). A carcinoma that arises from epithelial cells of the prostate gland. "In the prostate cancer cohort, the mutation frequencies of ARID2, CNTN6, CHD1 and other genes were significantly different in different IP-score groups." (PMID 36700205, 2022).
pulmonary neoplasm (1 paper, 2017). "Genetic testing of the pulmonary neoplasm demonstrated ARID2 genomic alterations." (PMID 28494807, 2017).
renal cell carcinoma (1 paper, 2024). "To thoroughly investigate the role of ARID2 in TFE3-rearranged renal cell carcinoma (TFE3-RCC) cells, we designed a series of in vitro and in vivo experiments." (PMID 39727945, 2024). "ARID2 plays a crucial tumor-suppressive role in TFE3-rearranged Renal Cell Carcinoma (TFE3-RCC)." (PMID 39727945, 2024).
serous adenocarcinoma (1 paper, 2025). An adenocarcinoma that is characterized by the presence of papillary patterns and cellular budding. "An exclusive MDM2 amplification was identified within the serous adenocarcinoma fraction, while an ARID2 loss and an AKT2 amplification were uniquely present in the SC-NEC compartment." (PMID 40833530, 2025).
Sézary syndrome (1 paper, 2023). "Other SWI/SNF genes recurrently altered in CTCLs are SMARCE1 and SMARCD2 (each amplified in 20% Sézary syndrome patients, N = 25), ARID2 (deleted in 8% Sézary syndrome patients, N = 25), and SMARCB1 (point mutation frequency ~ 3%, combined N = 433)." (PMID 36810086, 2023).
speech disorder (1 paper, 2025). A term referring to disorders characterized by the disruption of normal speech. "In the literature, the ARID2 associated phenotype mainly consists of psychomotor delay (96%), hypotonia (70%), speech disorders (87%), behavior problems (65%), variable range of ID from mild to severe (96%), ectodermal features (hair 50%, and nail anomalies 38%), and few dental anomalies (24%)." (PMID 40044822, 2025).
tumor (99 papers, 2011 to 2026). "This patient's tumor revealed ARID2 mutations with microsatellite stability, which limits the applicability of immune checkpoint inhibitors in disease management." (PMID 40260333, 2025). "ARID2 is particularly involved in transcriptional regulation linked to cell cycle control, DNA damage response, and tumor suppression." (PMID 39857780, 2025). "In the same TME, Arid2 deficiency conferred enhanced proliferative ability and decreased terminal exhaustion in tumour‐specific CD8+ T cells compared with their wild‐type control." (PMID 39169517, 2024). "The transfer of Arid2 (encoding PBAF)‐deleted CD8+ P14 T cells resulted in significantly lower tumour burdens compared with the control group." (PMID 39169517, 2024). "Together, these findings indicate that the loss of Arid2 generates less exhausted, highly proliferative tumor-infiltrating effector CD8+ T cells, resulting in improved tumor control." (PMID 37330910, 2023). "This suggests that given the same tumor microenvironment, Arid2 deficiency confers higher proliferative capacity and reduced terminal exhaustionin tumor-responding CD8+ T cells than their wild-type counterparts." (PMID 37330910, 2023). "It will be important to investigate ARID2 loss during development of the melanocyte lineage in vivo and to evaluate its effects on viability in order to better understand its tumor-suppressive activities." (PMID 35323214, 2022). "Of note, the variant frequencies in the clonal tumor population (ARID2, SETD2, and TERT promoter) and in the subclonal population (NF2) were validated by targeted NGS for this patient." (PMID 34261524, 2021). "ARID2 is currently considered as a tumor suppressor gene since its nonsense mutations found in ∼10% melanoma samples are predicted to be loss-of-function mutations and lack the capability for DNA binding." (PMID 34858604, 2021). "ARID2-mutated cancers are therefore expected to offer a greater tumor susceptibility to immunotherapies." (PMID 32977645, 2020). "The ARID2 protein is involved in the regulation of chromatin remodeling and its loss of function is associated with increased tumor cell sensitivity to interferon-γ and expression of T-cell cytotoxicity genes." (PMID 33315984, 2020). "These genetic alterations did not confer a worse OS in patients with higher grade T classification (T>0), tumor grade or ARID2, TERT mutations." (PMID 32850303, 2020). "Disease characteristics: ARID2 mRNA levels are associated with age, sex, tumour grade, disease stage and HBV status." (PMID 32162380, 2020). "This same tumor also had six variants of uncertain significance: ARID2 c.1672C > T p.(R558C), FLT3 c.2546G > A p.(R849H), IGF1R c.3897C > G p.(N1298K), MSH6 c.1157C > G p.(P386R), PBRM1 c.2504G > A p.(R850H), and RNF43 c.1114C > T p.(P372S)." (PMID 31046843, 2019). "Correlative analysis of ARID2 protein levels with clinicopathologic features suggested that lower expression of ARID2 protein was closely associated with poor tumor differentiation (p < 0.01)." (PMID 27351279, 2016). "In our study, the patient also had an ARID2 gene missense mutation in both the primary tumor and peritoneal metastasis." (PMID 27270314, 2016). "As ARID2 has only recently been implicated as a tumor suppressor in hepatocarcinogenesis, relatively few studies have evaluated ARID2 expression in tumor tissues or explored the mechanism by which ARID2 affects downstream protein expression and function." (PMID 27351279, 2016). "Moreover, in both the tumour and tdLN, there were significantly more Arid2‐deficient CD8+ P14 cells." (PMID 39169517, 2024). "Panel sequencing of microdissected tissue of the resected tumor and the biopsy of the recurrence revealed a mutation of ARID2 (chromosome 12; position (GRCh37) 46205208, c.292G > A; p.E98K) with an allele frequency of 48% in the tumor recurrence under denosumab treatment." (PMID 33707617, 2021).
tumor (continued). "Recent genomic studies have identified frequent ARID2 mutations in HCC, but it remains unclear how ARID2 functions as a tumour suppressor gene." (PMID 32162380, 2020). "A genome‐scale CRISPR‐Cas9 screen to identify mechanisms of tumor cell resistance to killing by cytotoxic T cells identified the loss of over 100 genes, including PBRM1, ARID2, and BRD7, as sensitizing events to T cell‐mediated killing." (PMID 41387924, 2025). "Other members of the SWI/SNF complex, namely ARID1A/B and ARID2 are well-established tumor suppressor genes." (PMID 40514689, 2025). "Whereas the HMGA2::MSRB3 and HMGA2::FHIT fusions were described in previous studies, the remaining detected fusion partners such as ARID2 or IFNG-AS1 are novel in this tumor type." (PMID 40033554, 2025). "Through a series of in vitro and in vivo experiments, we confirmed that ARID2 acts as a tumor suppressor in TFE3-RCC." (PMID 39727945, 2024). "In other tumor models, mutations in the SWI/SNF chromatin remodeling complex, including PBRM1 and ARID2, have been found to sensitize tumor cells to T-cell-mediated killing." (PMID 38653864, 2024). "This study aims to elucidate the functional consequences of ARID2 deficiency in TFE3-RCC, investigating its impact on tumor biology, gene expression patterns, molecular mechanism, and potential therapeutic targets." (PMID 39727945, 2024). "A patient with an ARID2 frameshift-bearing HNSCC had tumor shrinkage of 29% and remains on study at this writing after 99 weeks." (PMID 37934611, 2024). "In patients with a high tumor mutational burden, other significantly mutated genes were APC (p = 0.029), and ARID2 (p = 0.029)." (PMID 39028418, 2024). "Remarkably, by day 7 after adoptive cell transfer (ACT), the recipients of Arid2-deleted P14 CD8+ T cells had a significantly lower tumor burden compared with the control group." (PMID 37330910, 2023). "In many human cancers, the expression of PBRM1 and ARID2 enhances the sensitivity of tumor cells to T cell killing, thereby inhibiting tumor progression." (PMID 37192179, 2023). "On the other hand, ARID2 is considered a tumor suppressor gene that regulates cell growth, differentiation, and apoptosis." (PMID 38023196, 2023). "Whole-exome sequencing revealed 99 somatic mutations including SMARCA4, ARID2, TET2, CDKN2A, WNT7A, NOTCH3 and STAG2, all present both in the primary tumor and in the cell line." (PMID 38201285, 2023). "We observed a significant increase in the frequency of the effector like CXCR6+CD44+ cluster in the tumor from Arid2-deleted CD8+ T cell recipients compared with the control (26.2% versus 8.72%)." (PMID 37330910, 2023). "Mutations of ARID2, CUL3, TET1, FBXW7, EZR and GPHN were frequently accompanied by copy number loss consistent with their predicted/documented tumour suppressor roles." (PMID 38106039, 2023). "Of the neoantigens with a strong affinity, four originated from tumor related genes (ARID2, DICER1, PAX8, and PTEN)." (PMID 37932340, 2023). "ARID2 was considered a tumor suppressor in early-onset sporadic rectal cancer through inhibiting tumor growth in vivo, cell migration, and viability." (PMID 36567903, 2022). "ARID2 is an important tumor suppressor in HCC, but recent genomic studies have found frequent mutations of ARID2 in HCC." (PMID 36034939, 2022).
tumor (continued). "Additional in vivo studies are clearly needed to elucidate the function of ARID2 in melanocyte development and in tumor suppression." (PMID 35323214, 2022). "Several studies have revealed the role of ARID2 as a significant tumour suppressor in many cancer subtypes." (PMID 32929219, 2021). "Here we demonstrate that ARID2 acts as an important tumor suppressor gene in LUADs and reveal that ARID2 depletion induces HSPA1A expression potentially through a transcriptional de-repression mechanism." (PMID 34858604, 2021). "Together, our findings establish ARID2 as an important tumor suppressor in LUADs with novel mechanistic insights, and further identify HSPA1A as a potential therapeutic target in ARID2-deficient LUADs." (PMID 34858604, 2021). "ARID2, NF1, and PIK3CG mutations are associated with poor tumor differentiation and the epithelial–mesenchymal transition." (PMID 34158601, 2021). "If the loss of ARID2 or PBAF complex can impair DDR, an aberrant transcriptional regulation is more likely to be responsible for the tumor suppressive properties." (PMID 32977645, 2020). "To assess the impact of PBAF complex mutations in non-RCC cohorts treated with ICB profiled with MSK-IMPACT, we restricted our analysis to 11 tumor types with at least 50 patients and at least 5 patients with PBRM1 or ARID2 mutations (n = 2936)." (PMID 32820162, 2020). "Similar to ARID2, BRD7 is also a component of the SWI/SNF remodeling machinery and a putative tumor suppressor reported with significant truncating mutations in HCC." (PMID 30521023, 2018). "ARID2 belongs to the SWI/SNF-related chromatin remodeling complexes and is identified as a tumor suppressor that is frequently mutated in HCC patients." (PMID 30521023, 2018). "One carcinoma displayed subclonal acquisition of TERT promoter, ARID2, and PTEN mutations in 13% of tumor cells." (PMID 29101368, 2017). "Our results reveal a tumor suppressor function of ARID2, which involves targeting the Rb-E2F signaling pathway and thus regulating E2F-downstream genes." (PMID 27351279, 2016). "Restoration of ARID2 expression in hepatoma cells was sufficient to suppress cell proliferation and tumor growth in mice, whereas ARID2 knockdown contributed to the enhancement of cellular proliferation and tumorigenicity." (PMID 27351279, 2016). "Taken together, these results imply that restoration of ARID2 expression inhibited tumor growth and aggressiveness in vitro and in vivo." (PMID 27351279, 2016). "Significant repression of tumor growth was observed to occur in nude mice following restoration of ARID2 expression." (PMID 27351279, 2016). "Data revealed that the levels of both ARID2 transcripts and proteins were markedly lower in the tumor tissues but much higher in the peritumoral liver tissues, as shown by both RT-PCR and western blot analysis." (PMID 27351279, 2016). "Our data suggest that ARID2 inhibits hepatoma cell-cycle progression and tumor growth by targeting the Rb-E2F signaling pathway." (PMID 27351279, 2016). "We additionally investigated the roles of ARID2 in the suppression of cellular proliferation and tumor growth in hepatoma cell lines." (PMID 27351279, 2016). "Strong genetic and functional data have been provided to support the notion that ARID2 is an important tumor suppressor gene in HCC." (PMID 22095441, 2011). "Moreover, transcription factor activity analysis revealed elevated activity of several transcription factors, such as ARID2, E2F1, E2F4, NFYB, and MYC, in the RRhighepi group, all of which are closely associated with cell proliferation and tumor progression." (PMID 41424847, 2026).